INS (insulin)
Diseases named in the same sentence as INS in open-access papers (continued):
Sharing a sentence is not in itself a finding about the gene and the disease.
Insulin resistance (continued). "Since defective autophagy may also underlie impaired insulin sensitivity in obesity and upregulating autophagy may be a useful strategy to combat insulin resistance, it highlights the importance to further characterise the biological effects of FEN." (PMID 26592777, 2016). "Deletion of Fetuin-A improves insulin resistance and dyslipidemia and enhances glucose clearance in mice, whereas with genetic variants in humans, Fetuin-A has been associated with type 2 diabetes and is linked with insulin action in adipocytes." (PMID 27973438, 2016). "Direct insulin treatment is undesirable for this group of disease states given the potential for creating a state of hypoglycemia and reduced efficacy as a function of insulin resistance associated with neurodegenerative disease." (PMID 30202553, 2016). "Such low-grade inflammation, which may possibly be beneficial in the early stage for promoting β-cell proliferation and insulin production to compensate for insulin resistance, is the mechanism underlying insulin resistance." (PMID 27544079, 2016). "This increase may be related to loss of albumin causing increased insulin resistance and higher demand for insulin in T2DM patients with albuminuria." (PMID 26739836, 2016). "Furthermore, the resulting hyperglycemia due to selective insulin resistance continues to stimulate insulin production from the pancreas, which causes the classic triad of hyperinsulinemia, hyperglycemia, and hypertriglyceridemia in patients with T2DM." (PMID 27312339, 2016). "Moreover, compound A treatment led to a robust suppression of glucose excursion during both OGTT and IPGTT in diet-induced mice, a commonly used model of insulin resistance and glucose intolerance, associated with an increase in plasma insulin." (PMID 27322810, 2016). "Cell shrinkage impairs insulin signaling and “may be a major cause of insulin resistance which develops in systemic hyperosmolality”." (PMID 26729162, 2016). "The insulin resistance may predispose to fatty liver via impairment of insulin-suppression of lipolysis, increasing free fatty acid flux towards the liver." (PMID 27788147, 2016). "Insufficient insulin production, or insulin resistance, is a prime cause of diabetic complications." (PMID 27881904, 2016). "The association between insulin resistance and fat mass suggests that changes in the adipocytokine milieu may have a role in the regulation of insulin secretion or a paracrine effect on adipocyte function." (PMID 27685706, 2016). "The observed correlation between weight loss and reduced insulin requirements suggests that although insulin resistance has traditionally only been associated with the pathophysiology of T2D, it may play a role in obese patients with T1D as well." (PMID 27375900, 2016). "In conclusion,increased musclin expression may be associated with insulin resistance in skeletalmuscle, and exercise training improves lipid metabolism and insulin sensitivityprobably by upregulating GLUT4 and downregulating musclin." (PMID 27143172, 2016). "Both ghrelin and obestatin are deregulated in obesity and associated with insulin and insulin resistance and thus may be considered a suitable target for the management of insulin resistance." (PMID 27348010, 2016). "As the G/C genotype of SREBP-2 is significantly associated with Serum levels of TG, elevated CRP, fasting insulin and homeostasis model assessment for insulin resistance levels, it can be a potential explanation for the close relationship between IR, TG, CRP and SREBP-2 polymorphism." (PMID 26965314, 2016). "As increased seminal insulin is associated with insulin resistance and abdominal obesity, increased insulin exposure during spermatogenesis may potentially develop insulin resistance in the SCs and within the spermatozoa themselves." (PMID 27891185, 2016). "Taken together, our data suggested that the glucose intolerance of those mice might be caused by both low serum insulin levels and insulin resistance." (PMID 27655719, 2016).
Insulin resistance (continued). "In conclusion, the present study shows that indices of heart rate variability during everyday life are associated with insulin sensitivity, and it suggests that a higher ratio of sympathetic to parasympathetic autonomic nerve activity promotes insulin resistance." (PMID 27352833, 2016). "To this aim we investigated the association of the FINDRISC with insulin secretion, insulin sensitivity, insulin resistance related traits, incident type 2 diabetes, drug-treated hypertension, CVD events and total mortality in a 6-year follow-up of a large Finnish population-based study." (PMID 27851812, 2016). "The same study reported a transgenerational effect of BPA; indeed, the six-month-old male offspring of mothers with insulin resistance developed insulin resistance and an impairment of glucose tolerance, associated with higher levels of plasma insulin compared with offspring of untreated mothers." (PMID 27782064, 2016). "Thus, insulin resistance in the liver is featured by loss of insulin-mediated suppression of gluconeogenesis." (PMID 27895587, 2016). "In addition, HFSD feeding increases plasma free fatty acid (FFA) concentrations and causes insulin resistance by inhibiting insulin-stimulated glucose uptake, glycogen synthesis, and/or phosphorylation activity." (PMID 27379252, 2016). "In our follow-up study of the large population-based METSIM cohort we evaluated the associations of the FINDRISC with changes in insulin secretion, insulin sensitivity, insulin resistance related traits and the risk of type 2 diabetes, drug-treated hypertension, CVD events, and total mortality." (PMID 27851812, 2016). "The role of ChREBP in the development of insulin resistance is less clear however, as global ChREBP deletion in mice causes glucose intolerance and insulin resistance, yet ChREBP deletion in ob/ob mice results in improved glucose tolerance and insulin sensitivity." (PMID 27992582, 2016). "While elevations in circulating GC levels induce insulin resistance, regular exercise enhances insulin sensitivity and causes reductions in both GR and IIβ-HSD1 expression within the skeletal muscle, liver, and adipose tissue, ultimately reducing tissue-specific GC exposure." (PMID 27929385, 2016). "However, knockin mice (P465L) carrying a similar human mutation P467L have normal insulin sensitivity in contrast with the severe insulin resistance in these patients." (PMID 27483259, 2016). "Also an increase in fasting insulin reflects hepatic insulin resistance, and previous studies have demonstrated a causal relationship between hepatic insulin resistance and liver fat content." (PMID 27579785, 2016). "It has been shown that ATM‐deficient mice exhibit glucose intolerance, insulin resistance and impaired insulin secretion 5, 6, while interactions of this protein kinase with multiple components of insulin signalling (JNK, PI3K, IRS2 and AKT) have been observed in in vitro studies." (PMID 26606753, 2016). "Western diet, which is characterised by a hyper-caloric intake high in fats and simple sugars, precipitates a rapid increase in post-prandial plasma glucose and insulin levels, increasing hepatic de novo-lipogenesis, steatosis, insulin resistance, central obesity and the risk of NAFLD." (PMID 27314342, 2016). "However, feline obesity has been associated with insulin resistance, impaired glucose tolerance and an abnormal insulin response during a glucose tolerance test." (PMID 27136422, 2016). "Furthermore, both pharmacological approaches did not influence the expression of the PTPs SHP‐1, SHP‐2, PTP1B, TC‐PTP, DEP‐1 and LAR, which all have been implicated as regulators in insulin signalling or insulin resistance earlier." (PMID 27047746, 2016). "First, systemic inflammation is responsible for increasing insulin resistance which may affect colorectal cancer risk via the growth-promoting effects of elevated insulin, glucose, or triglycerides." (PMID 27483316, 2016).
Insulin resistance (continued). "Thus it has been well argued that this primary predisposition to excess insulin secretion per se is both bad for β-cell health and predisposes insulin resistance." (PMID 27559358, 2016). "At baseline, ANGPTL8 concentrations were positively associated with triglycerides (TG) (r = 0.168, P = 0.010), whereas ANGPTL3 levels were associated with fasting insulin (r = 0.248, P < 0.001) and the homeostasis model assessment of insulin resistance (HOMA-IR) (r = 0.197, P = 0.002)." (PMID 26739706, 2016). "Next, to test whether insulin resistance in AdicerKO mice was associated with aging, we performed insulin tolerance tests in young (4 month-old) and old (18-month-old) mice that had AL access to chow during their entire lifespan." (PMID 27241713, 2016). "Previous studies investigating the associations of irisin with metabolic outcome including insulin or the Homeostatic Model Assessment for Insulin Resistance (HOMA-IR) as well exercise related outcomes also reported significant associations in men but not women." (PMID 27128661, 2016). "Given the effect of insulin on modulating ovarian and adrenal steroidogenesis, a role of intrauterine adverse events which lead to insulin resistance and/or hyperinsulinemia may predispose adolescents to PCOS." (PMID 27423183, 2016). "Firstly, the findings from whole body studies that hypoxia causes insulin resistance may be the product of increased insulin release combined with a decrease in insulin action at the site of insulin sensitive target tissue." (PMID 27274997, 2016). "In addition, high methylation levels at this CpG site were shown to be associated with increased fasting insulin and insulin resistance." (PMID 27777315, 2016). "In this study, we employed adiponectin knockout (APN-KO) mice to mimic the condition of chronic APN deficiency in T2DM patients and aged subjects, and demonstrated that there were cerebral insulin resistance and deregulated insulin signaling upon APN deficiency." (PMID 27884163, 2016). "In addition, more recently, diets with a low insulin load were reported to be associated with lower body fat during puberty and with lower energy intake in obese adolescents with features of insulin resistance and/or prediabetes." (PMID 27749919, 2016). "Moreover, the lipolysis caused by endothelial lipase and stimulated by insulin is attenuated due to insulin resistance." (PMID 26985241, 2016). "Reasoning that MARCH1 upregulation in insulin resistance would be consistent with loss of normal repression by insulin, we tested whether insulin regulates MARCH1 expression." (PMID 27577745, 2016). "The ability of DCI to modulate in vitro ovarian activity of insulin could at least in part explain its beneficial effect when used as treatment for conditions associated to insulin-resistance." (PMID 27582109, 2016). "Indices of glucose metabolism calculated from the OGTT at 30–32 weeks revealed that PTX3 levels was positively associated with insulin sensitivity (r = 0.23, p < 0.001) and β-cell function (r = 0.18, p = 0.003), and negatively with insulin resistance (r = −0.23, p < 0.001)." (PMID 26842615, 2016). "The association of TCF7L2 genetic variant with increased insulin resistance and decreased insulin secretion may help understand GDM pathogenesis." (PMID 27465520, 2016). "The study also observed an inverse association between vitamin B12, HOMA-IR and insulin levels in children, indicating that deficiency of vitamin B12 at an early age may cause insulin resistance." (PMID 27608037, 2016). "Light to moderate drinking may enhance insulin sensitivity and reduce the risk of non-alcoholic steatohepatitis, possibly due to reduced insulin resistance." (PMID 26892109, 2016). "Indeed it has been shown that specifically restoring hypothalamic leptin action in leptin receptor deficient rats improved whole body insulin resistance by enhancing hepatic insulin sensitivity." (PMID 27273128, 2016).
Insulin resistance (continued). "Regarding chronic insulin detemir therapy, however, it remains to be determined whether permanent hyperinsulinemia might in turn cause brain insulin resistance." (PMID 27589235, 2016). "Therefore, the present study aims to examine the associations of the DII with markers of glucose-insulin homeostasis, and with the risk of glucose tolerance abnormalities and insulin resistance in an Iranian population." (PMID 27869717, 2016). "In particular, long-term up-regulation of GPx may cause insulin resistance and disruptions in insulin signaling." (PMID 26997979, 2016). "To verify whether insulin resistance is directly caused by impaired autophagy function in macrophages, we first examined insulin signaling in Atg7KO mice." (PMID 27229537, 2016). "At 30 weeks, HOMA-IR values revealed a ∼sevenfold increase in whole body insulin resistance for ED diet-fed mice compared with control mice, in association with increased pancreatic islet area and elevated pancreas insulin content suggestive of a compensatory hyperinsulinaemic state." (PMID 27402965, 2016). "However, high systemic doses would be needed to achieve functionally effective insulin concentrations in the brain, causing strong peripheral side effects such as hypoglycemia and induction and/or exacerbation of peripheral insulin resistance." (PMID 26136647, 2015). "Moreover, GM3S deficient mice exhibit enhanced insulin signaling and less susceptibility to insulin resistance induced by a high fat diet." (PMID 26102277, 2015). "However, this study did not explore other MetS components and limited the CKD risk-factors to just insulin-related variables, such as serum-insulin, HbA1C and insulin resistance." (PMID 26431218, 2015). "Additionally, even in the absence of elevations in circulating estrogens, obesity is a risk factor for endometrial cancer through obesity-induced insulin resistance and the resultant higher insulin levels." (PMID 26134033, 2015). "The diet-induced changes in coronary microvascular perfusion occur at a time when cardiac insulin sensitivity gets compromised, but prior to the development of hypertension and cardiac remodeling, which are commonly associated with more advanced insulin resistance and type 2 diabetes." (PMID 26576929, 2015). "Furthermore, the possible relationships of the gene variants with insulin resistance and serum levels of insulin were also evaluated." (PMID 27141540, 2015). "This polymorphism may also contribute to impaired insulin secretory capacity and increased insulin resistance in a Chinese population." (PMID 26204833, 2015). "It was also reported that vWF was associated with insulin level and insulin resistance." (PMID 25646961, 2015). "In summary, we herein demonstrated for the first time the beneficial effects of L-Cit on improved insulin resistance associated with enhanced insulin sensitivity through the activation of IRS1 followed by the inhibition of serine 1101 phosphorylation both in vivo and in vitro." (PMID 26084330, 2015). "Type 2 diabetes is caused by impaired insulin secretion and insulin resistance." (PMID 26561346, 2015). "Thus, insulin therapy at the appropriate time can reverse pathophysiology underlying pathway-selective insulin resistance in heart that contributes to ischemic damage, myocardial dysfunction and HF." (PMID 26659007, 2015). "Central administration of insulin fails to reduce food intake under conditions of obesity, and intranasal application of insulin to the human brain improves peripheral insulin sensitivity in lean but not in obese men, indicating that obesity also causes central insulin resistance." (PMID 26236282, 2015). "Postoperative GU values in the intestine correlated with whole-body insulin sensitivity, indicating that the intestinal mucosa may reflect the overall glycaemic state and potentially mediate obesity-associated insulin resistance." (PMID 25631620, 2015).
Insulin resistance (continued). "Insulin resistance is characterized by deficient responses to insulin in its target tissues." (PMID 26084330, 2015). "It seems that fatty acids released from adipose tissue in obese patients causes insulin resistance through disruption in insulin signaling cascade, increased inflammation, oxidative stress, coagulation abnormalities, endothelial damage, myocardial dysfunction and accelerated atherosclerosis." (PMID 25886602, 2015). "Furthermore, the strong association between PCOS and insulin resistance indicates that insulin directly influences ovarian function, while impaired glucose tolerance and insulin secretion have been shown to be associated with vitamin D deficiency." (PMID 25918586, 2015). "It is also interesting to note that even when matched for pubertal stage and body composition, individuals with BBS exhibit elevated plasma insulin levels relative to the control subjects, which is consistent with the notion that insulin resistance associated with BBS is a primary defect." (PMID 26103456, 2015). "The major finding of the present study was that supplementation with C. forskohlii extract in conjunction with a hypocaloric diet significantly improved insulin and insulin resistance and thus may be useful in the management of metabolic risk factors." (PMID 26593941, 2015). "There is evidence of the relationship between the presence of the polymorphism Arg972 and insulin resistance, where the individuals with the polymorphism present low levels of fasting glucose and C-peptide, as well as impaired insulin synthesis and secretion in the presence of glucose." (PMID 25859280, 2015). "Furthermore, high-fat diet intake has been pointed as an important risk factor for insulin resistance, since it both impairs insulin signaling pathway and stimulates inflammation, via Toll-like receptors signaling cascade." (PMID 25960614, 2015). "Therefore, insulin resistance is always associated with impaired NO availability, suggesting that a reciprocal relationship exists between insulin activation and endothelial function." (PMID 26091235, 2015). "In conclusion, reduced HRV was associated with insulin resistance and lower insulin sensitivity." (PMID 26277879, 2015). "Additionally, using the reference values from IDEFICS to calculate the frequency of the cardiometabolic risk factors, high insulin levels (40.5 %) and insulin resistance (41.4 %) were the most frequent." (PMID 26546280, 2015). "Although the pathophysiology of diabetic dyslipidaemia is not fully understood, the insulin resistance and relative insulin deficiency observed in patients with type 2 diabetes are likely to contribute to these lipid changes, as insulin plays an important role in regulating lipid metabolism." (PMID 25725623, 2015). "Since hypertrophic adipocytes have reduced insulin-dependent glucose uptake up via GLUT4 that is associated with whole body insulin resistance, the increased GTT response in HFD-fed CD24KO may be due to dysfunctional adipocytes." (PMID 26536476, 2015). "In addition to peripheral insulin resistance, brain pathologies associated with AD affect insulin secretion by impeding the cross-talk between the brain and islets via the sympathetic nervous system and adipokines." (PMID 25755673, 2015). "Thus, immune cells that can infiltrate insulin-sensitive tissues such as fat, the liver, and muscle are associated with tissue inflammation and contribute to insulin resistance during obesity." (PMID 26197341, 2015). "In the case of inflammation-associated insulin resistance, there are several instances of crosstalk between insulin signaling composed of IRS1-4 proteins, PI3K, AKT/protein kinase B (PKB), and mitogen-activated protein kinases (MAPKs, i.e., p38, JNK, and IKKβ) of inflammatory signaling." (PMID 25623542, 2015).